HIC1 (HIC ZBTB transcriptional repressor 1)
Description:
Transcriptional repressor. Recognizes and binds to the consensus sequence '5- [CG]NG[CG]GGGCA[CA]CC-3'. May act as a tumor suppressor. Involved in development of head, face, limbs and ventral body wall (By similarity). The specific target gene promoter association seems to be depend on corepressors, such as CTBP1 or CTBP2 and MTA1. In cooperation with MTA1 (indicative for an association with the NuRD complex) represses transcription from CCND1/cyclin-D1 and CDKN1C/p57Kip2 specifically in quiescent cells. Involved in regulation of the Wnt signaling pathway probably by association with TCF7L2 and preventing TCF7L2 and CTNNB1 association with promoters of TCF-responsive genes. Seems to repress transcription from E2F1 and ATOH1 which involves ARID1A, indicative for the participation of a distinct SWI/SNF-type chromatin-remodeling complex. Probably represses transcription of ACKR3, FGFBP1 and EFNA1.
Synonyms: Hic-1; ZBTB29; ZNF901
Tractability: PROTAC: UniProt records ubiquitination sites on it.
Gene: Protein-coding gene on chromosome 17 (2,054,154 to 2,063,241, forward strand). Ensembl gene ENSG00000177374.
Subcellular location: Nucleus
Pathways (Reactome):
Metabolism of proteins: SUMOylation of transcription factors
Gene Ontology:
Molecular function: DNA-binding transcription factor activity; DNA-binding transcription repressor activity, RNA polymerase II-specific; histone deacetylase binding; protein binding; sequence-specific DNA binding; sequence-specific double-stranded DNA binding; DNA-binding transcription factor activity, RNA polymerase II-specific
Biological process: intrinsic apoptotic signaling pathway in response to DNA damage; negative regulation of transcription by RNA polymerase II; negative regulation of Wnt signaling pathway; regulation of DNA-templated transcription; regulation of transcription by RNA polymerase II; regulation of signal transduction
Cellular component: nucleus; chromatin; nucleoplasm
Genetic constraint (gnomAD): Loss-of-function variants: 9 observed, 17.43 expected, observed/expected ratio (o/e) 0.52, 90% interval 0.31 to 0.9. The synonymous counts are far from expectation, so gnomAD's model fits this gene poorly and the ratio says little. Missense variants: 965 observed, 813.07 expected, observed/expected ratio (o/e) 1.19, 90% interval 1.12 to 1.25. Synonymous variants: 631 observed, 412.33 expected, observed/expected ratio (o/e) 1.53, 90% interval 1.43 to 1.63.
Homologues: Orthologues: chimpanzee HIC1 (100% identical), macaque HIC1 (99% identical), pig HIC1 (97% identical), dog HIC1 (97% identical), mouse Hic1 (95% identical), guinea pig HIC1 (95% identical), rat Hic1 (95% identical), tropical clawed frog hic1 (61% identical), zebrafish hic1 (52% identical), zebrafish zgc:66474 (16% identical). Paralogues in human: HIC2 (39% identical), ZBTB7C (19% identical), ZBTB18 (15% identical), ZBTB42 (14% identical), ZBTB16 (13% identical), PRDM1 (13% identical), ZBTB1 (13% identical), PATZ1 (13% identical), PRDM10 (13% identical), ZNF410 (12% identical), PRDM14 (12% identical), ZBTB20 (12% identical), and 24 more.
Diseases named in the same sentence as HIC1 in open-access papers:
HIC1 is named in the same sentence as 116 diseases in open-access papers, as found by Europe PMC text mining. Sharing a sentence is not in itself a finding about the gene and the disease. The quoted sentences say what the papers report.
breast carcinoma (32 papers, 2001 to 2025). "A putative tumor suppressor gene called HIC1 (hypermethylated in cancer) is situated at 17p13.3, a locus where the allelic loss occurs often in human malignancies, including breast cancer." (PMID 38646326, 2024). "In this study, we aimed to determine the role of the IL-6/pSTAT3/HIC1 axis in the breast cancer microenvironment, including in cancer-associated fibroblasts (CAFs) and breast cancer cells." (PMID 31795965, 2019). "It is known that the loss of HIC-1, caused by promoter hypermethylation, is associated with tumor aggression and poor survival in breast carcinoma." (PMID 25435951, 2015). "Inactivation of HIC-1 in breast carcinomas is associated with tumor metastasis, and a previous study demonstrated that restoring the HIC-1 expression by demethylation treatment impaired the aggressiveness of head and neck squamous cell carcinoma." (PMID 25435951, 2015). "Consistent with this, the inactivation of HIC-1 in breast carcinoma predisposed cells to stress-induced metastasis via the up-regulation of ADRB2." (PMID 24489730, 2014). "Hypermethylation of HIC1 and the associated decrease in HIC1 expression is a common feature in several cancers, such as human breast cancer, acute myeloid leukemia, and prostate cancer." (PMID 22140553, 2011). "In addition, loss of HIC1 in breast cancer cells contributes to stress-induced migration and invasion through β-2 adrenergic receptor (ADRB2) misregulation." (PMID 31680974, 2019). "The HIC-1 protein expression has been linked to better outcomes in breast cancers." (PMID 22016618, 2011). "A number of studies suggest that low expression of HIC1 in cancer tissues may be associated with hypermethylation of the promoter region of the gene, such cancers include breast cancer, colon cancer, cervical cancer, and diffuse large cell type B cell lymphoma." (PMID 31795965, 2019). "Moreover, low to undetected expression of HIC-1 is associated with poor outcome in breast cancer." (PMID 20546602, 2010). "And HIC1 was positively associated with GSDMD across multiple cancer types, including bladder cancer (BLCA), breast cancer (BRCA), lung squamous cell carcinoma (LUSC), pancreatic cancer (PAAD), and colon cancer (PARD)." (PMID 40279559, 2025). "Previous studies have demonstrated the involvement of HIC1 in the development of various malignant tumors, including breast cancer, lung cancer, and PCa, highlighting its role as a novel tumor suppressor." (PMID 41050263, 2025). "In a pre-clinical study analyzing different breast cancer subtypes, it was observed that HIC1 expression is silenced only in TNBC, in contrast to the other BC subtypes." (PMID 38473804, 2024). "In particular, HIC1 protein expression is more significantly reduced in TNBC than in other breast cancer or normal breast cells." (PMID 39339179, 2024). "We determined HIC1 protein expression levels in various breast cancer cell lines (MCF7, SKBR3, BT474, MDA-MB-231, MDA-MB-468, HCC38, and MDA-MB-453) compared to human normal breast cells (MCF12A)." (PMID 39339179, 2024). "The IHC staining of HIC1 was mainly weakly or negatively expressed in tumor tissue from breast cancer, LUSC, LUAD, and COAD while was relatively higher in their corresponding normal tissues." (PMID 37388742, 2023). "Isolation of stromal fibroblasts from breast cancer tissue and analysis of the supernatant showed that IL-6 downregulated the tumor suppressor HIC1 and promoted the development of breast cancer in the TME through paracrine or autocrine signals." (PMID 37978384, 2023). "It has been reported that there were significant correlations between tumor sizes more than 2 cm, lymph node involvement, and HIC1 methylation among a sub population of Iranian breast cancer patients." (PMID 33883026, 2021). "HIC1 is continually silenced in human cancers, including breast cancer, prostate cancer, colorectal cancer, liver cancer, and lung cancer, and this is assumed to be ascribed to promoter hypermethylation." (PMID 31680974, 2019).
breast carcinoma (continued). "First, we analyzed the patient samples in TCGA database, the results discovered that HIC1 was significantly down-expressed in breast cancers, suggesting that the malignancy of breast cancer was related to HIC1 abnormal expression." (PMID 31680974, 2019). "HIC1 is epigenetically silenced in many human cancers, including breast cancer, prostate cancer, colorectal cancer, liver cancer, and lung cancer, and this is assumed to be ascribed to promoter hypermethylation." (PMID 31680974, 2019). "The results found that the HIC1 protein levels were significantly decreased in the breast cancer tissues." (PMID 31680974, 2019). "In breast cancer, HIC1 deletion had been reported to promote breast cancer progression by activating tumor cell/fibroblast crosstalk." (PMID 31680974, 2019). "Subsequently, 14 pairs of clinical breast cancer samples were collected to detect the HIC1 expression level by immunoblotting." (PMID 31680974, 2019). "Our findings provided important insights into the mechanisms through which miR-4532 regulates HIC-1 expression to affect drug resistance in breast cancer cells." (PMID 30202238, 2018). "HIC-1 was also found to be differentially expressed in breast cancer tissues and to be correlated with prognosis." (PMID 30202238, 2018). "In this study, we firstly investigated that miR-4532 involved in the multidrug resistance formation of breast cancer by targeting hypermethylated in cancer 1 (HIC-1), a tumor-suppressor gene." (PMID 30202238, 2018). "Our findings are the first to demonstrate the interactions between miR-4532 and its target HIC-1 in the context of chemotherapeutic drug resistance in breast cancer." (PMID 30202238, 2018). "Kaplan–Meier analysis of 159 patients with breast cancer in Sweden demonstrated that high HIC-1 expression was related to a high RFS rate compared with low HIC-1 expression (p = 0.0141)." (PMID 30202238, 2018). "Cell proliferation and invasion assay experiments showed overexpression of HIC-1 inhibited the invasion and metastasis of breast cancer cells." (PMID 30202238, 2018). "Our previous studies disclosed that dsHIC1-2998, an saRNA, effectively activated HIC-1 with evident suppression of cell growth and induction of apoptosis in breast cancer." (PMID 25435951, 2015). "The saRNA-HIC-1 effectively activated the HIC-1 gene with evident suppression of cell growth and induction of apoptosis in breast cancer." (PMID 25435951, 2015). "In conclusion, cell models were created for the restoration of the tumor suppressor gene, HIC-1, in breast cancer cells." (PMID 25435951, 2015). "More recently, our research group successfully reactivated the HIC-1 tumor suppressor in gastric cancer and in breast cancer." (PMID 25435951, 2015). "Hypermethylated in cancer 1 (HIC-1), a tumor suppressor gene for breast cancer, located on 17p13.3, encodes a transcriptional suppressor protein, with five Kruppel-like C2H2 zinc finger motifs and the N-terminal protein-protein interaction domain, BTB/POZ." (PMID 25435951, 2015). "Here, we screened gene expression in breast cancer, and confirmed that HIC-1 is generally downregulated in breast cancer." (PMID 24489730, 2014). "HIC-1 is a gene that is hypermethylated in cancer, and commonly downregulated in human breast cancer." (PMID 24489730, 2014). "HIC-1 is a tumor suppressor gene that is expressed at low levels in breast cancer and other malignancies due to epigenetic silencing [11−16]." (PMID 24489730, 2014). "In the present study, 62.5% of breast cancer samples revealed low levels of expression of HIC-1 in tissue microarray analysis." (PMID 24489730, 2014). "In present study, we successfully activated the tumor suppressor gene HIC-1 using saRNA (dsHIC1-2998) in breast cancer cells." (PMID 24489730, 2014). "HIC-1 is a gene that is hypermethylated in cancer, and is commonly downregulated in human breast cancer." (PMID 24489730, 2014).
breast carcinoma (continued). "HIC-1 is ubiquitously expressed in normal tissues, but low-expressed in different tumor cells, including hepatocellular carcinoma, colorectal carcinoma, breast cancer and gastric cancer." (PMID 22016618, 2011). "Concentration of cirDNA and methylation of RARβ2, RASSF1A and HIC-1 gene promoters were investigated in cell-free and cell-surface-bound fractions from healthy donors, patients with breast cancer, and patients with breast fibroadenoma." (PMID 16641902, 2006). "HIC-1 expression was examined using RT-PCR on RNA extracted from 50 primary untreated, human breast cancers and was detected in only 7/50 (14%) cancers." (PMID 11747329, 2001). "In comparison to other breast cancer subtypes, HIC1 is frequently epigenetically silenced in TNBC." (PMID 41303420, 2025). "Downstream targets of HIC1 include genes responsible for developmental and cell cycle control, but its regulatory mechanism in different breast cancer subtypes remains unclear." (PMID 41303420, 2025). "HIC1 expression has been found to be silenced only in triple-negative breast cancer compared with other breast cancer molecular subtypes, and HIC1 slicing could facilitate triple-negative breast cancer progression by targeting lipocalin-2 (LCN2)." (PMID 37388742, 2023). "Hypermethylated in cancer 1 (HIC1) is continually decreased in breast cancer." (PMID 31680974, 2019). "Moreover, in high-IL-6-secreting MDA-MB-231 breast cancer cells, HIC1 was restored upon knocking down IL-6 expression, accompanied by decreased STAT3 activity." (PMID 31795965, 2019). "Consequently, the expression of HIC1 was markedly inhibited by overexpressing miR-128, while miR-128 inhibition markedly upregulated the HIC1 protein levels in breast cancer cells." (PMID 31680974, 2019). "Additionally, restoration of HIC1 dramatically weakened the pro-proliferative, pro-invasive, and anti-apoptotic effect of miR128 in breast cancer cells and completely block tumor growth in nude mice." (PMID 31680974, 2019). "HIC1 is known to inhibit cell proliferation and invasion and induce apoptosis, so we measured the effects of miR-128-driven repression of HIC1 expression on the proliferation, invasion, and apoptosis of breast cancer cells." (PMID 31680974, 2019). "In this paper, we showed that miR-128 ectopic increased in human breast cancer tumors and can target a tumor suppressor gene named HIC1, resulting in the downregulation of HIC1 protein level and consequently promotes proliferation and invasion and inhibits apoptosis of breast cancer cells." (PMID 31680974, 2019). "Here, we found that miR-128 participates in HIC1 repression in breast cancer cells." (PMID 31680974, 2019). "Because miRNAs generally showed opposite expression patterns with their targets, we then studied whether miR-128 was inversely correlated with HIC1 in breast cancer." (PMID 31680974, 2019). "Here, we showed that HIC1 was downregulated in breast cancer tissues." (PMID 31680974, 2019). "To further determine the relationship between HIC-1 expression and the clinical prognosis of patients with breast cancer, we evaluated the prognostic value of HIC-1 in a public clinical microarray database of breast cancer cases collected between and 2005 from 2017." (PMID 30202238, 2018).
breast carcinoma (continued). "In brief, the novel information regarding the link between miR-4532 and HIC-1 in breast cancer cells would be beneficial for the better understanding of drug resistance formation of breast tumor, which provides a novel strategy for clinical application in the future." (PMID 30202238, 2018). "Therefore, in this study, we aimed to elucidate the effects of miR-4532 on the regulation of HIC-1 during acquisition of MDR in breast cancer." (PMID 30202238, 2018). "The HIC-1 gene, located on chromosome 17p13.3, is a tumor-suppressor gene that is frequently silenced or deleted in a variety of human cancers, such as leukemia, liver cancer, pancreatic cancer, and breast cancer." (PMID 30202238, 2018). "HIC-1 protein was downregulated in all breast cancer tissues." (PMID 30202238, 2018). "The upregulation of HIC-1 by saRNA molecules may be a therapeutic strategy for the suppression of breast cancer progression." (PMID 25435951, 2015). "HIC-1 has been observed to be epigenetically silenced in human cancers including breast cancer." (PMID 25435951, 2015). "Subsequently, the HIC-1 tumor suppressor was successfully reactivated in breast cancer cells." (PMID 25435951, 2015). "Decreased expression of the HIC-1 gene is observed in non-small cell lung cancer, hepatocellular carcinoma, gastric cancer and human medulloblastomas, and the loss of HIC-1 expression is a common event in primary breast cancer." (PMID 25435951, 2015). "We assessed HIC-1 expression on a tissue microarray containing 80 cases of breast cancer." (PMID 24489730, 2014). "Restoring the tumor suppressor function of HIC-1 gene may partially derive benefit from reduced CENPF expression on breast cancer cells." (PMID 24489730, 2014). "Data demonstrated that HIC-1 expression was reduced significantly in breast cancer tissues." (PMID 24489730, 2014). "RASSF1, CDH1 and HIC1 are frequently silenced due to hypermethylation in breast cancer patients." (PMID 25068292, 2014). "This suggests that restoring HIC-1 expression induced apoptosis in breast cancer cells." (PMID 24489730, 2014). "The expression of HIC-1 protein was reduced significantly in breast cancer tissue." (PMID 24489730, 2014). "One report demonstrated that HIC-1 regulates breast cancer cell responses to endocrine therapies." (PMID 22016618, 2011). "Restoration of HIC-1 in breast cancer cells led to a growth arrest in vivo." (PMID 22016618, 2011). "Hypermethylated in Cancer 1 (HIC1), located on chromosome 17p13.3 completely within a CpG island, is a tumor repressor that is widely expressed in normal tissues, however, is generally lowly expressed with methylation in several cancers, such as prostate cancer, breast cancer, and pancreatic cancer." (PMID 37388742, 2023). "Additionally, HIC1 expression was found to be silenced only in triple-negative breast cancer (TNBC) compared with other molecular subtypes of breast cancer, HIC1 contributed to reduced cell migration, invasion and metastasis in triple-negative breast cancer (TNBC) cells." (PMID 35071242, 2021). "Moreover, HIC1 could function as tumor suppressor in breast cancer through transcriptional repression of ephrin-A1." (PMID 31680974, 2019). "Therefore, we speculate that there are different IL-6-mediated HIC1 regulatory mechanisms in different breast cancer cell lines." (PMID 31795965, 2019). "The profile of HIC1 in human breast cancer suggested that HIC1 might act as cancer suppressor." (PMID 31680974, 2019). "Moreover, regulation of HIC1 by miR-128 may explain, at least in part, why miR-128 upregulation can increase cell proliferation and invasion and inhibit apoptosis in breast cancer." (PMID 31680974, 2019). "However, HIC-1 protein expression was retained in some breast carcinoma samples." (PMID 24489730, 2014).